UBA3 (ubiquitin like modifier activating enzyme 3)
Description:
Catalytic subunit of the dimeric UBA3-NAE1 E1 enzyme. E1 activates NEDD8 by first adenylating its C-terminal glycine residue with ATP, thereafter linking this residue to the side chain of the catalytic cysteine, yielding a NEDD8-UBA3 thioester and free AMP. E1 finally transfers NEDD8 to the catalytic cysteine of UBE2M. Down-regulates steroid receptor activity. Necessary for cell cycle progression.
Synonyms: UBE1C; hUba3; NAE2
Tractability: Small molecule: a drug acting on it is in phase 2 or 3 trials; a structure with a bound ligand is known; a high-quality ligand is known; it has a high-quality binding pocket. Antibody: the Human Protein Atlas places it where antibodies can reach. PROTAC: ubiquitination databases record sites on it; its protein half-life has been measured; a small molecule that binds it is known.
Target class: Enzyme; Ligase
Chemical probes: ABPA3 (high quality), PEVONEDISTAT (high quality)
Gene: Protein-coding gene on chromosome 3 (69,054,716 to 69,080,408, reverse strand). Ensembl gene ENSG00000144744.
Subcellular location (Human Protein Atlas): Cytosol; Plasma membrane; Centrosome; Nucleoplasm
Pathways (Reactome):
Immune System: Antigen processing: Ubiquitination & Proteasome degradation; Dectin-1 mediated noncanonical NF-kB signaling; NIK-->noncanonical NF-kB signaling
Disease: Dengue Virus Attachment and Entry
Metabolism of proteins: Neddylation
Gene Ontology:
Molecular function: identical protein binding; NEDD8 activating enzyme activity; protein binding; protein heterodimerization activity; NEDD8 transferase activity; ubiquitin-like modifier activating enzyme activity
Biological process: protein neddylation; post-translational protein modification; protein modification process; proteolysis
Cellular component: nucleus; protein-containing complex; cytosol
Genetic constraint (gnomAD): Loss-of-function variants: 13 observed, 44.63 expected, observed/expected ratio (o/e) 0.29, 90% interval 0.19 to 0.46. The upper end of that interval is the gene's LOEUF score, 0.46, which puts it in group 2 of 6, group 1 being the genes least tolerant of losing a copy. Missense variants: 351 observed, 396.5 expected, observed/expected ratio (o/e) 0.89, 90% interval 0.81 to 0.97. Synonymous variants: 160 observed, 136.96 expected, observed/expected ratio (o/e) 1.17, 90% interval 1.03 to 1.33.
Homologues: Orthologues: chimpanzee UBA3 (100% identical), macaque UBA3 (100% identical), mouse Uba3 (99% identical), rabbit UBA3 (99% identical), rat Uba3 (99% identical), dog UBA3 (98% identical), pig UBA3 (98% identical), tropical clawed frog uba3 (90% identical), zebrafish uba3 (87% identical), guinea pig UBA3 (68% identical), Drosophila melanogaster Uba3 (61% identical), Caenorhabditis elegans rfl-1 (49% identical). Paralogues in human: UBA2 (33% identical), UBA1 (26% identical), UBA6 (25% identical), UBA7 (25% identical), MOCS3 (13% identical), ATG7 (13% identical), UBA5 (10% identical), NAE1 (9% identical), SAE1 (7% identical).